ENSG00000288914 (novel protein)
Gene: Protein-coding gene on chromosome 7 (105,040,858 to 105,040,956, forward strand). Ensembl gene ENSG00000288914.
Genetic constraint (gnomAD): Loss-of-function variants: 2 observed, 2.07 expected, observed/expected ratio (o/e) 0.97, 90% interval 0.36 to 1.87. That is too few expected variants to judge how well the gene tolerates losing a copy. Missense variants: 8 observed, 9.26 expected, observed/expected ratio (o/e) 0.86, 90% interval 0.51 to 1.54. Synonymous variants: 5 observed, 4.43 expected, observed/expected ratio (o/e) 1.13, 90% interval 0.57 to 1.87.